TFPI2 (tissue factor pathway inhibitor 2)
Diseases named in the same sentence as TFPI2 in open-access papers (continued):
Sharing a sentence is not in itself a finding about the gene and the disease.
cervical cancer (11 papers, 2012 to 2024). A primary or metastatic malignant neoplasm involving the cervix. "The inactivation of the TFPI-2 gene has been demonstrated using two well-known epigenetic regulatory mechanisms in cervical cancer cells and tumor-associated cervical fibroblasts." (PMID 39684425, 2024). "In summary, we demonstrated that inactivation of the TFPI2 gene occurs via cooperative action of cervical cancer cells and tumor-associated cervical fibroblasts, utilizing two well-known epigenetic regulatory mechanisms." (PMID 32559232, 2020). "There was a close association between the expression of TFPI-2 and tumor cell apoptosis and angiogenesis in patients with cervical cancer." (PMID 22208663, 2012). "In addition, the data showed that apoptosis was associated with TFPI-2 in cervical carcinoma." (PMID 22208663, 2012). "TFPI-2 can be considered a tumor suppressor since it plays a role in the suppression of invasiveness by cervical cancer." (PMID 39684425, 2024). "For instance, ZNF582 exhibits high methylation levels in GC and cervical cancers, while TFPI2 displays elevated methylation in GC and CRC." (PMID 38774285, 2024). "The next question is, why two different epigenetic processes are needed for TFPI2 inactivation in cervical cancer." (PMID 32559232, 2020). "To characterize the involvement of TFPI-2 in cervical cancer, we established three fibroblast cultures: NF, MF and TF." (PMID 32559232, 2020). "Establishment of the comprehensive panel of NF, MF, TF and T cell cultures allowed the detailed study of the role of TFPI-2 in the behavior of cervical cancer." (PMID 32559232, 2020). "As a consequence, inactivation of the TFPI2 gene plays a strategic role in the progression of cervical cancer." (PMID 32559232, 2020). "This presumption was supported by the immunohistochemical analysis of cervical cancer specimens where the expression of TFPI-2 gradually decreased toward to invasion front both in cancer cells and CAFs." (PMID 32559232, 2020). "And the expression of TFPI2 had a decreasing trend with tumor progression of cervical cancer through inhibiting tumor cell apoptosis and angiogenesis." (PMID 29137404, 2017). "The treatment of HPV-positive cervical cancer cell lines with demethylating agents, coupled to expression microarrays, has allowed the identification of genes encoding for SPARC and TFPI2 as highly methylated in invasive cervical cancer." (PMID 24383054, 2013). "TFPI-2 expression has a decreasing trend with the progression of cervical cancer and was significantly correlated with FIGO stage, lymph node metastasis and HPV infection." (PMID 22208663, 2012). "It is believed that TFPI-2 contributes to tumor cell apoptosis and angiogenesis in patients with cervical cancer." (PMID 22208663, 2012). "As a result, we propose that TFPI-2 silencing was probably one of the mechanisms of cervical cancer." (PMID 22208663, 2012). "It was reported that, TFPI-2 showed high frequency of CpG islands aberrantly methylated in both cervical cancer specimens and cell lines." (PMID 22208663, 2012). "The results suggested that the expression of TFPI-2 had a decreasing trend with tumor progression of cervical cancer." (PMID 22208663, 2012). "Future studies focused on the molecular mechanism whereby TFPI-2 expression and function affects tumor cell gene expression of cervical cancer are needed." (PMID 22208663, 2012). "The treatment of cervical cancer cell lines with demethylating agents, coupled to expression microarrays, has identified the genes encoding SPARC and TFPI2 as highly methylated in invasive cervical cancer." (PMID 22815913, 2012). "And further study will be essential for discovering more valuable information about TFPI-2 expression and cell proliferation in cervical carcinoma." (PMID 22208663, 2012). "Epigenetic silencing of TFPI-2 has also been described in cervical cancer." (PMID 39153052, 2024).
cervical cancer (continued). "Moreover, pioneering studies employing retroviral transduction of Zinc-finger proteins engineered with TET-2-CD have shown reactivation of candidate TSGs, such as C13ORF18 and TFPI2 in cervical cancer cells, and ICAM-1 in ovarian cancer cells." (PMID 37120619, 2023). "Furthermore, compared to HSILs, CCNA1 and TFPI2 are the most prominently methylated genes in cervical cancers." (PMID 32559232, 2020). "The previous results indicated that TFPI-2 must be downregulated in human cervical cancer cases." (PMID 32559232, 2020). "Our current report aims to elucidate the mechanism of TFPI-2 silencing in cervical cancer." (PMID 32559232, 2020). "In addition, it is revealed that aberrant methylation of TFPI-2 was present in a high proportion of cervical cancer clinical samples and cell lines." (PMID 22208663, 2012). "We then studied the correlation between TFPI-2 and apoptosis, ki-67, VEGF and MVD expression to evaluate whether TFPI-2 contributed to tumor cell apoptosis, proliferation and angiogenesis in patients with cervical cancer." (PMID 22208663, 2012). "But, to our knowledge, little is known on the role of TFPI-2 silencing in cervical cancer." (PMID 22208663, 2012). "To investigate the relationship between TFPI-2 and tumor cell apoptosis, proliferation and angiogenesis in patients with cervical cancer, we analyzed the immunohistochemical expression levels of TFPI-2, with relationship to AI, PI, VEGF and MVD in cervical biopsy tissues." (PMID 22208663, 2012). "Our data suggested that TFPI-2 inhibited tumor apoptosis and metastasis of cervical cancer and might be a regulatory molecule in the malignant potential of cervical cancer." (PMID 22208663, 2012). "Thus, the findings suggested that TFPI-2 play an important role with apoptosis in cervical carcinoma." (PMID 22208663, 2012). "Therefore, we believe that decreased TFPI-2 expression correlates with increased expression of VEGF in cervical carcinoma, suggesting that active TFPI-2 plays a suppressive role on VEGF gene expression." (PMID 22208663, 2012). "It was reported that MT1G, NMES1, RRAD, SFRP1, SPARC and TFPI2 were more often methylated in invasive cervical cancer samples than in normal ones, suggesting that these 6 genes may be potential tumor suppressor candidate for cervical cancer." (PMID 26329329, 2015). "TFPI-2 may play an inhibitive role during the development of cervical cancer." (PMID 22208663, 2012). "TFPI-2 may be considered as a tumor suppressor gene during the development of cervical cancer." (PMID 22208663, 2012). "TFPI2 hypermethylation has been observed in CRC, GC, hepatocellular carcinoma, pancreatic cancer, and cervical cancer." (PMID 29137404, 2017). "Our data indicated that the grading of TFPI-2 gene expression had a decreasing trend with FIGO stages, lymph node metastasis and HPV infection of cervical cancer." (PMID 22208663, 2012). "In the present study, we found that TFPI-2 expression in all patients with normal epithelial cells and CIN was positive, while that was activated in 66.2% of cervical carcinomas in immunohistochemical analysis." (PMID 22208663, 2012). "However, we did not establish any significant correlation between Ki-67 and TFPI-2 expression in cervical cancer." (PMID 22208663, 2012).
gastric cancer (9 papers, 2014 to 2025). A primary or metastatic malignant neoplasm involving the stomach. "The main TFPI2 mechanism related to the disease is hypermethylation, which has been confirmed in Barrett’s esophagus and gastric cancer." (PMID 37349838, 2023). "Recently, studies have shown that TFPI2 is down-regulated in prostate cancer, pancreatic ductal adenocarcinoma, gastric cancer, non-small-cell lung cancer, etc., and is closely related to various malignant tumors progression." (PMID 32248791, 2020). "The transcriptional silencing of TFPI-2 by hypermethylation in the promoter region has been recently demonstrated in many human cancers, including nasopharyngeal, colorectal and gastric carcinoma." (PMID 24695110, 2014). "RASSF1A, p14ARF, and MGMT; CHRNA3, DOK1, and GNMT; p16, hMLH1, MINT1, MINT2, MINT12, MINT25, and MINT31; APC, CDH1, MHL1, CDKN2A, CDKN2B, and RUNX3; CDH1; DKK3; PTEN; MGMT; TFPI2; CACNA2D3; PCDH10; SOX2; MAL; and COX2 were previously reported to be hypermethylated in gastric cancer." (PMID 26121593, 2015).
prostate carcinoma (9 papers, 2005 to 2025). A carcinoma that arises from epithelial cells of the prostate gland. "Previous studies of loss of imprinting in prostate cancer have focused on TFPI2 and IGF2, with one study reporting lower methylation in the former and three studies providing inconsistent reports of methylation changes in the latter." (PMID 23890537, 2013). "While loss of imprinting (LOI) has been reported for two genes in prostate cancer (IGF2 and TFPI2), disease-related changes in methylation across all imprinted gene regions has not been investigated." (PMID 23890537, 2013). "Similarly, miR-616-3p suppresses TFPI2 in prostate cancer and preeclampsia, affecting proliferation, migration, and EMT." (PMID 40361374, 2025). "Thus, it appears that miR616 induces androgen – independent growth of prostate cancer cells by suppressing expression of TFPI-2." (PMID 39153052, 2024). "Different molecular mechanisms can lead to loss of TFPI-2 expression in cancer, including deletions, mutations in the promoter and epigenetic silencing, and recent evidence indicates that TFPI-2 can also be downregulated by miR-616 in prostate cancer." (PMID 23703216, 2013). "Deletion of the TFPI-2 gene and as a result, a complete lack of TFPI-2 protein expression has been implicated in the genesis of uterine leiomyoma and prostate cancer." (PMID 39153052, 2024).
ovarian carcinoma (8 papers, 2018 to 2025). A malignant neoplasm originating from the surface ovarian epithelium. "In a study of 256 ovarian cancer patients, serum TFPI2 ≥ 255 pg/mL was associated with shorter progression-free survival (PFS) in clear cell carcinoma, and ≥ 201 pg/mL was linked to reduced overall survival (OS) in non-clear cell carcinoma." (PMID 40361374, 2025). "This assay has been used to assess TFPI2 levels in blood, with a diagnostic threshold of 191 pg/mL showing 64.7% sensitivity, 91.5% specificity, and an AUC of 0.893 for distinguishing ovarian cancer from benign ovarian tumors." (PMID 40361374, 2025). "Initially characterized as a tumor suppressor gene, TFPI2 is herein re-examined in light of the paradox that elevated circulating levels are associated with poor prognosis in several malignancies, including ovarian cancer." (PMID 40361374, 2025). "In Japan, following a multicenter prospective clinical trial, TFPI2 has been reimbursed by health insurance as a serum-based diagnostic biomarker for ovarian cancer since 2021." (PMID 40361374, 2025). "Elevated TFPI2 levels have also been linked to poor prognosis in ovarian cancer." (PMID 40361374, 2025). "Indeed, in patients with ovarian cancer, elevated serum TFPI2 levels were reported to be associated with an increased risk of VTE." (PMID 37238908, 2023). "Tissue factor pathway inhibitor 2 (TFPI2) is a novel blood diagnostic biomarker for ovarian cancer." (PMID 35565252, 2022). "In the context of malignancies, we specifically highlight ovarian cancer, endometrial cancer, and renal cell carcinoma, where TFPI2 expression is notably upregulated." (PMID 40361374, 2025). "Since 2021, TFPI2 testing has been incorporated into Japan’s public health insurance system for ovarian cancer diagnosis." (PMID 40361374, 2025). "Tissue factor pathway inhibitor 2 (TFPI2) has emerged as a novel serum biomarker for ovarian cancer, gaining insurance coverage in Japan in 2021." (PMID 40361374, 2025). "With the establishment of robust TFPI2 quantification assays, it has become evident that circulating concentrations of TFPI2 are markedly elevated in ovarian cancer, as well as in endometrial and renal cell carcinomas." (PMID 40361374, 2025). "The methylation of opioid-binding protein/cell adhesion molecules like OPCML, Runt-related transcription factor 3 (RUNX3), and tissue factor pathway inhibitor 2 (TFPI2) genes was studied in ovarian cancer patients using methylation-specific NGS." (PMID 38275400, 2024). "Fourth, a clinically applicable TFPI2 ELISA kit for ovarian cancer diagnosis was launched at Tosoh Corporation in 2021." (PMID 37238908, 2023). "A multicenter prospective cohort study revealed that TFPI2 is a novel serum biomarker for predicting ovarian cancer." (PMID 37238908, 2023). "Ovarian cancers produce large amounts of TFPI2, so its concentrations in cancer tissues are expected to be much higher than those in peripheral blood." (PMID 37238908, 2023). "Notably, TFPI2 has emerged as a promising biomarker for predicting asymptomatic venous thromboembolism (VTE) in ovarian cancer patients." (PMID 40361374, 2025). "Serum TFPI2 levels were significantly increased in patients with OCCC compared with other histologic types of ovarian cancer or benign endometriosis, suggesting that TFPI2 may be useful for the early diagnosis of OCCC." (PMID 35565252, 2022). "Elevated serum TFPI2 levels are being explored as biomarkers for VTE and poor prognosis in ovarian cancer." (PMID 40361374, 2025). "TFPI2 may also distinguish patients with VTE from those without VTE among patients with epithelial ovarian cancer and positive D-dimer results." (PMID 35565252, 2022). "In a cohort of 142 ovarian cancer cases (77 clear cell carcinomas [CCC] and 65 non-CCCs), TFPI2 expression was observed in 52 cases (36.6%)." (PMID 40361374, 2025).
ovarian carcinoma (continued). "Furthermore, ovarian cancer patients who experienced VTE had elevated TFPI2 levels compared to those without thromboembolic events, suggesting that TFPI2 may be a biologic marker for predicting VTE." (PMID 37238908, 2023).
bladder cancer (7 papers, 2007 to 2025). "In TFPI-2 overexpressing cells, the invasion of bladder cancer BIU-87 cells was significantly reduced in vitro." (PMID 39153052, 2024). "In two more studies about the role of TFPI2 in tumors (bladder cancer and renal cell carcinoma), a pro-apoptotic role was demonstrated." (PMID 32784482, 2020). "In general, normal tissues and cell lines contained higher levels of full-length TFPI-2 while tumor tissues and tumor cell lines, with the exception of the bladder carcinoma J82 cell line, contained 4–50 fold higher levels of the asTFPI-2 transcripts." (PMID 17352822, 2007). "Similarly, TFPI-2 expression level is negatively related to the progression of bladder cancer." (PMID 39153052, 2024). "On the other hand, over-expression of either human TFPIβ (TFPI) or a mouse TFPIβ (mTFPI), but not TFPI2, elevated the sensitivity to TcdB4.2 in HeLa cells, and in a human bladder carcinoma cell line 5637 (a cell line that we found to be not sensitive to TcdB4.2)." (PMID 36351897, 2022).
atherosclerosis (6 papers, 2012 to 2025). A disease characterized by the build-up of fatty material and calcium deposition in the arterial wall resulting in partial or complete occlusion of the arterial lumen. "Beyond its involvement in cancer, aberrant expression of TFPI2 has been observed in a range of pathological conditions, including diabetes, atherosclerosis, and pregnancy-induced hypertension." (PMID 40361374, 2025). "Beyond tumorigenesis, TFPI2 contributes to both inflammatory progression and resolution in diabetes, atherosclerosis, and preeclampsia." (PMID 40361374, 2025). "Previous studies of vascular tissue samples revealed alterations in methylation of ALOX15, ESR1, ESR2, MCT3 and TFPI2 genes in patients with atherosclerosis." (PMID 25856389, 2015). "It has proved that TFPI-2 played an important role in suppressing thrombosis and arterial re-stenosis, which has been considered as a potential gene for gene therapy of atherosclerosis." (PMID 23594865, 2013). "Tissue factor pathway inhibitor-2 (TFPI-2) may play critical roles in the pathogenesis of atherosclerosis." (PMID 26496276, 2015). "TFPI2 plays a multifaceted role in the pathogenesis of various non-neoplastic conditions, including pregnancy-related disorders such as gestational hypertension, diabetes, and atherosclerosis." (PMID 40361374, 2025). "In vascular tissues of patients with atherosclerosis, DNA methylation alterations of 15-lipoxygenase (ALOX15), estrogen receptors (ESR1 and ESR2), monocarboxylate transporter 3 (MCT3), and tissue factor pathway inhibitor 2 (TFPI2) genes have been reported using a candidate gene approach." (PMID 25856389, 2015).
colon carcinoma (6 papers, 2007 to 2024). "Consistent with this, LCT13 expression in breast and colon cancer cell lines is associated with silencing and repressive chromatin at TFPI-2." (PMID 23703216, 2013). "By using the LCT13b Taqman assay, we analysed HCT116 and CaCo-2 colon cancer cells and found that expression of LCT13b is also associated with down-regulation of TFPI-2 in these lines." (PMID 23703216, 2013). "Research indicates that Tissue Factor Pathway Inhibitor 2 (TFPI2) demonstrates relatively higher sensitivity for left-sided colon cancer." (PMID 38542332, 2024). "A half-life value of ~16 h was obtained for asTFPI-2 in a colon carcinoma cell line, in comparison to ~8 h for TFPI-2 mRNA in HUVECs." (PMID 17352822, 2007).
non-small cell lung carcinoma (6 papers, 2005 to 2025). A group of at least three distinct histological types of lung cancer, including non-small cell squamous cell carcinoma, adenocarcinoma, and large cell carcinoma. "Our results were similar to the study of non-small-cell lung cancer, in which the downregulation of TFPI-2 mRNA was more frequently associated with advanced stages." (PMID 22208663, 2012). "LncRNA TFPI2AS1 upregulates TFPI2, inhibiting G1/S transition and suppressing non-small cell lung cancer growth." (PMID 40361374, 2025). "Experimental models using ES-2 ovarian clear cell carcinoma and NCI-H460 non-small cell lung carcinoma cells have demonstrated that TFPI2 knockout enhances cancer cell proliferation and invasion by inducing the clustering of integrin α1 or β1." (PMID 40361374, 2025). "In non-small-cell lung cancer, TFPI-2 promoter hypermethylation was frequently found in patients with late-stage cancer (stages III and IV) and with lymph node metastases." (PMID 21062455, 2010). "In this study, TFPI-2 mRNA was measured using a real-time PCR method in tumours of 59 patients with non-small-cell lung cancer (NSCLC)." (PMID 15685245, 2005).